CIMAP1C (ciliary microtubule associated protein 1C)
Synonyms: ODF3L1; MGC48986
Tractability: No criterion of Open Targets' tractability assessment is met for any kind of drug.
Gene: Protein-coding gene on chromosome 15 (75,724,041 to 75,727,688, forward strand). Ensembl gene ENSG00000182950.
Gene Ontology:
Molecular function: protein binding
Cellular component: cytoskeleton
Genetic constraint (gnomAD): Loss-of-function variants: 6 observed, 7.31 expected, observed/expected ratio (o/e) 0.82, 90% interval 0.45 to 1.58. That is too few expected variants to judge how well the gene tolerates losing a copy. Missense variants: 326 observed, 363.61 expected, observed/expected ratio (o/e) 0.9, 90% interval 0.82 to 0.98. Synonymous variants: 131 observed, 143.4 expected, observed/expected ratio (o/e) 0.91, 90% interval 0.79 to 1.06.
Homologues: Orthologues: chimpanzee CIMAP1C (99% identical), macaque CIMAP1C (95% identical), dog CIMAP1C (78% identical), pig CIMAP1C (78% identical), mouse Cimap1c (72% identical), rat Cimap1c (70% identical), guinea pig CIMAP1C (64% identical), rabbit CIMAP1C (63% identical). Paralogues in human: CIMAP1D (34% identical), CIMAP1A (31% identical), CIMAP1B (30% identical), STPG1 (16% identical), STPG2 (15% identical).
Diseases named in the same sentence as CIMAP1C in open-access papers:
CIMAP1C is named in the same sentence as 1 disease in open-access papers, as found by Europe PMC text mining. Sharing a sentence is not in itself a finding about the gene and the disease.
CIMAP1C shares sentences with these, for which no sentence is quoted: tumor (1 paper).